FLG (filaggrin)
Diseases named in the same sentence as FLG in open-access papers (continued):
Sharing a sentence is not in itself a finding about the gene and the disease.
atopic dermatitis (continued). "The R501X and/or 2282del4 filaggrin null mutations were present in 26 (15%) of children with atopic dermatitis and were primarily associated with predilection to exposed skin areas (especially the cheeks and back of the hands) and an up-regulation of both acute and chronic dermatitis." (PMID 23166590, 2012). "Furthermore, FLG mutations are major predisposing factors for atopic dermatitis (AD) and are associated with early onset of AD, persistence of AD into adulthood and asthma and allergic sensitization." (PMID 23166590, 2012). "The strong association between clinical atopic dermatitis and filaggrin skin barrier gene mutation carriage has opened up new avenues to explore gene-environment interactions, not only in the context of atopic dermatitis, but also allergic respiratory disease and food allergy." (PMID 23121771, 2012). "It has been discovered that common loss-of-function mutations within the FLG gene cause ichthyosis vulgaris, one of the most common heritable disorders of cornification, and represent major risk factors for atopic dermatitis (AD) and secondary allergic diseases." (PMID 19384417, 2009). "Consistent with this hypothesis, the exC3 cluster contained two genes (SPINK5 and FLG) previously recognised to confer susceptibility to childhood atopic dermatitis (AD), and one (CDSN) which has been implicated in psoriasis." (PMID 19888454, 2009). "Atopic dermatitis (AD) is a chronic inflammatory skin disorder characterized by impaired epidermal barrier function, immune dysregulation (e.g., Th2 polarization), genetic factors (e.g., filaggrin mutations), environmental triggers and microbial dysbiosis, leading to pruritus and eczematous lesions." (PMID 41155460, 2025). "Moreover, Dębińska, 2021 study on restoring Filaggrin deficiency to improve skin barrier function included many therapeutic strategies that could be promising for atopic dermatitis treatment." (PMID 38907248, 2024). "As filaggrin, a filament-associated protein, plays an important role in the maintenance of the skin barrier function, mutations within the filaggrin gene leading to the loss of its function are considered a risk factor for AD, atopic eczema, food allergies, and bronchial asthma." (PMID 35056019, 2022). "In addition, our results reveal that HRNR and FLG2 variants and FLG loss-of-function mutations are candidate genes that might control the risk of atopic eczema in an interactive manner." (PMID 36013110, 2022). "The interleukins IL-4 and IL-13 reduce the expression of filaggrin and weaken the permeability barrier of keratinocytes; these effects might be responsible for the pathogenic actions of IL-4 and IL-13 in atopic dermatitis." (PMID 36362566, 2022). "There have been studies associated with FLG in regulating skin disorders by using gene therapy and protein therapeutics, including gene therapy targeting the upregulation of the FLG expression in the human immortalized keratinocyte cell line and mice for remedying atopic dermatitis." (PMID 33195157, 2020). "FLG mutation and inflammatory process activated by upregulated genes may result in atopic eczema." (PMID 29057259, 2017). "Not only genetic studies screen the associations between Filaggrin loss-of-function mutations, atopic dermatitis, allergic sensitization, food allergy and even airway diseases, but also epidemiological studies cast new light on the hypothesis of the atopic march." (PMID 30402617, 2017). "Additionally to the known dysfunctions in barrier function of the skin (e.g. filaggrin mutations) and immunologic disturbances (e.g. Th2-shift), evidence is rising that atopic dermatitis is also connected to a dysbiosis of the microbial community without an invading pathogen." (PMID 25905004, 2014). "When someone has atopic dermatitis, changes in filaggrin and skin lipids allow allergens to enter the skin and lead to a Th2-mediated reaction." (PMID 40734872, 2025).
atopic dermatitis (continued). "Atopic dermatitis (AD) is known to result from reduced filaggrin and disrupted lipids, which compromise the skin barrier." (PMID 40734872, 2025). "The development of allergic diseases, such as atopic dermatitis, is associated with PM2.5-induced TNF-α, which contributes to a deficiency of filaggrin (FLG) in the skin and leads to further impairment of the skin barrier function." (PMID 40313388, 2025). "Examples include defects of filaggrin in atopic dermatitis and the downregulation of cornulin and SPRRs in oesophageal epithelial cancers." (PMID 41319262, 2025). "Atopic dermatitis is characterized by epidermal barrier impairment, with reduced filaggrin (FLG) and ceramide content and increased transepidermal water loss, which facilitates allergen entry and microbial colonization." (PMID 41304852, 2025). "The pathogenesis of atopic dermatitis combines dysfunction of the skin barrier (e.g., altered expression of the filaggrin gene, reduction in ceramides) that facilitates transcutaneous water loss and favors the entry of allergens, irritants, and microorganisms." (PMID 40095628, 2025). "Filaggrin gene (FLG/FLG2) product deregulations are associated with various allergic skin diseases, including but not limited to atopic dermatitis, alopecia areata, and ichthyosis vulgaris." (PMID 40765578, 2025). "Filaggrin gene (FLG/FLG2) mutations and expression are associated with various allergic skin diseases, such as atopic dermatitis, alopecia areata, and ichthyosis vulgaris." (PMID 40765578, 2025). "Although earlier studies have suggested a role for HDAC6 in modulating STAT3 acetylation in allergic dermatitis, the direct relationship between HDACs and FLG expression has remained unclear." (PMID 40730500, 2025). "Mutations or deficiencies in FLG and LOR are associated with impaired skin function and the onset of various skin diseases, including atopic dermatitis and psoriasis." (PMID 40637102, 2025). "Relatively common mutations of the SEDC genes, late cornified envelope (LCE) 3B and LCE3C, and of the SFTP gene, Filaggrin (FLG), are associated with elevated risk of psoriasis and atopic dermatitis, respectively." (PMID 38228724, 2024). "Many patients with atopic dermatitis have been found to have genetic abnormalities of filaggrin, and filaggrin is attracting attention as a key substance in the treatment of atopic dermatitis." (PMID 38790256, 2024). "A recent whole-genome sequencing study emphasized the association between variants within FLG, FLG2, HRNR, and TCHH1 and higher atopic dermatitis severity scores." (PMID 38790293, 2024). "Mutations encoding the filaggrin (filament aggregating protein, FLG) gene are major factors predisposing one to developing atopic eczema." (PMID 38791412, 2024). "We investigated this in the context of atopic dermatitis (AD) and the insufficient expression of the multifunctional epidermal barrier protein filaggrin." (PMID 38585273, 2024). "In this study, through an in-depth study of the structure and function of filaggrin, a new treatment option for atopic dermatitis was proposed, i.e., the use of recombinant human filaggrin (rhFLA-10), which contains a functional fragment of filaggrin." (PMID 38790293, 2024). "The precursor of FLG, profilaggrin, is encoded by the FLG gene on chromosome 1q21, and this loss-of-function (LOF) mutation is a major genetic risk factor for the development and persistence of atopic dermatitis." (PMID 38790293, 2024). "In NC/Nga mice with atopic dermatitis, calcitriol also substantially enhanced the mRNA expression of both filaggrin and loricrin." (PMID 37298299, 2023). "Filaggrin (FLG) is a crucial component of the skin’s protective barrier against external factors, and its deficiency is strongly linked to conditions such as atopic dermatitis." (PMID 37762597, 2023).
atopic dermatitis (continued). "Importantly, this association was particularly observed in high-risk children with history of atopic dermatitis and its severe course and was strongly modified by the presence of null mutations in FLG gene, supporting the hypothesis of epicutaneous sensitization through impaired skin." (PMID 36904070, 2023). "The structural protein filaggrin is localized in the upper layers of the differentiated epidermis and is known to play an important role in the pathogenesis of atopic dermatitis skin." (PMID 36615633, 2023). "While multiple mechanisms are involved, one remarkable protein, filaggrin (FLG) proved paramount; FLG mutation(s) confer the highest inherited risk for atopic dermatitis (AD)." (PMID 37338870, 2023). "The downregulation of E-cadherin, which is required for tight junction formation, is correlated with filaggrin insufficiency in AD and is shown in eczematous dermatitis." (PMID 37629159, 2023). "Filaggrin (FLG) is crucial for the skin’s protective barrier, and its deficiency is linked to conditions like atopic dermatitis." (PMID 38132480, 2023). "Immunohistochemical analysis showed that filaggrin, involucrin, loricrin, claudin-1, occludin, and ZO-1 were decreased in NC/Nga mice with atopic dermatitis, which is consistent with previous reports." (PMID 37298299, 2023). "Accepting the overwhelming evidence that FLG deficiency is a primary cause for the skin barrier abnormalities, restoring skin barrier function through upregulation of FLG expression could be beneficial strategies in both treating atopic dermatitis and preventing food allergy." (PMID 36904070, 2023). "In patients with atopic dermatitis, it has been reported that the mRNA expression of filaggrin, loricrin, occludin, and claudin-1 was decreased, while the expression of involucrin and TJP1 was not affected compared with control subjects." (PMID 37298299, 2023). "The expression of filaggrin, involucrin, and loricrin was decreased in the epidermis of NC/Nga mice with atopic dermatitis." (PMID 37298299, 2023). "Risk and severity have been associated with genetic variation especially with respect to the filaggrin gene, suggesting the importance of skin barrier function in atopic dermatitis pathogenesis." (PMID 35948745, 2022). "Filaggrin is an epidermal protein involved in skin barrier formation and hydration, whose expression is altered in canine atopic dermatitis (CAD)." (PMID 35878340, 2022). "The human filaggrin-2 (FLG2) protein is another member of the SFTP family that shares common structural features with FLG and is believed to be involved in atopic eczema pathogenesis." (PMID 36013110, 2022). "Atopic dermatitis (AD) is a common T-helper 2 (Th2) lymphocyte-mediated chronic inflammatory skin disease characterized by disturbed epidermal differentiation (e.g., filaggrin (FLG) expression) and diminished skin barrier function." (PMID 35163694, 2022). "Finally, mutations in the FLG gene—which encodes filaggrin, a structural protein with an important role in the skin’s barrier—is the strongest genetic risk factor associated with atopic dermatitis; in fact, 20% to 40% of all patients with atopic dermatitis have FLG loss-of-function mutations." (PMID 36235669, 2022). "As the interest in the skin barrier and keratinization has increased in the past decade, several studies have investigated the role of filaggrin in canine atopic dermatitis." (PMID 34357916, 2021). "The expression level of filaggrin, a key regulator of the skin barrier in atopic dermatitis, in the LBE group (7962 ± 328/2 × 107 pixels) was significantly lower than that in the control group (34,276 ± 818/2 × 107 pixels)." (PMID 34946332, 2021). "The expression level of KLK7, a physiological activator of caspase 14, and the enzyme initiating the degradation of filaggrin, is mostly increased in human and murine atopic dermatitis tissues." (PMID 34946332, 2021).
atopic dermatitis (continued). "Reduced expression of components of the cornified envelope, loricrin, filaggrin and involucrin are frequently down-regulated in human atopic dermatitis." (PMID 34445339, 2021). "In the case of glucose, topical glucose was shown to induce claudin-1 and filaggrin expression in a mouse model of atopic dermatitis and in keratinocyte culture, indicating that it has an anti-inflammatory effect by repairing skin barrier function." (PMID 32138354, 2020). "A critical role of filaggrin and ceramides in skin barrier function has been elucidated from investigations on ichthyoses, atopic dermatitis, and experimental conditions." (PMID 32054030, 2020). "For instance, in atopic dermatitis (AD), several components of skin barrier function, such as filaggrin, tight junction, and the microbiome are compromised in terms of quantity and/or quality, leading to increased cutaneous permeability." (PMID 32595651, 2020). "These beneficial effects that improve epidermal permeability and regulate filaggrin can be useful in the treatment of certain skin disorders, such as cutaneous inflammation and atopic dermatitis." (PMID 33022944, 2020). "OVOL1 regulates FLG expression in atopic dermatitis subjects, and in normal human epidermal keratinocytes." (PMID 33133517, 2020). "Filaggrin abnormalities are closely related to transepidermal water loss (TEWL) and dry skin in patients with atopic dermatitis." (PMID 32326002, 2020). "Filaggrin (FLG) is a key protein involved in epithelial barrier, and loss-of-function mutation of FLG caused ichthyosis vulgaris, Atopic dermatitis, skin microbiota and inflammation dysregulated diseases." (PMID 31956350, 2020). "Filaggrin, a highly abundant protein of the stratum corneum, draw considerable attention after the discovery of its role in the aetiology of atopic dermatitis." (PMID 33178610, 2020). "BLMH is a filaggrin cleavage enzyme that generates natural moisturizing factors and whose levels are reduced in dry skin and atopic dermatitis." (PMID 32033114, 2020). "In this review we summarised (emphasized) recent findings in understanding the role of filaggrin in atopic dermatitis and other diseases, participants in the atopic march." (PMID 31223255, 2019). "Recent studies reveal a significant decline in the expression of filaggrin in the skin tissues of both atopic dermatitis and psoriasis mouse models." (PMID 31216667, 2019). "This study demonstrated the role of filaggrin protein, eosinophil major basic protein and immunoglobulin E in the pathogenesis of pediatric patients with atopic dermatitis, allergic rhinitis and bronchial asthma." (PMID 30473631, 2018). "Loss-of-function variants of the filaggrin mutation (FLG) results in an impaired epidermal barrier function and have been shown to be a risk factor for the development of atopic dermatitis, allergies, and asthma." (PMID 30524933, 2018). "Our cell cultures experiments revealed that a downregulation in GATA3 by shRNA leads to a significant reduction of filaggrin mRNA under atopic dermatitis-like conditions in keratinocytes." (PMID 28928464, 2017). "Recent studies found that the FLG gene often showed a reduced expression in patients with atopic dermatitis and eczema." (PMID 28085100, 2017). "Defects in filaggrin and STAT3 are associated with atopic dermatitis (AD) and susceptibility to severe skin infection." (PMID 28081250, 2017). "In line with this, >90% of the atopic dermatitis (AD) patients, who often have reduced filaggrin expression, are colonized by S. aureus, whereas about 25% of the normal population is persistently colonized by this bacterium." (PMID 26741798, 2016). "Here, we studied mutations in the filaggrin gene (FLG), which are strong risk factors for atopic dermatitis (AD) and allergies, in a large number of families with AD." (PMID 25757221, 2015). "Loss-of-function mutations in the filaggrin gene (FLG) cause skin barrier deficiency and strongly predispose to atopic dermatitis (AD)." (PMID 25757221, 2015).
atopic dermatitis (continued). "In atopic dermatitis patients, coal tar completely restores the expression of major skin barrier proteins including filaggrin." (PMID 24966027, 2014). "In this study, we investigated the effect of loss-of-function mutations in the filaggrin gene (FLG), atopic dermatitis and wet work exposure on the development of hand eczema in apprentice nurses." (PMID 24102300, 2014). "Earlier microarray analyses revealed similar alterations in the expression of EDC genes in human atopic dermatitis, and notably the repressed expression of filaggrin, loricrin and involucrin." (PMID 23398847, 2013). "Its increased expression, as observed in atopic dermatitis, led to decreased expression of an important epidermal barrier component, filaggrin, and increased expression of pro-inflammatory cytokines, including TNFα and CCL5." (PMID 24260356, 2013). "Filaggrin gene (FLG) mutations have been identified as the cause of ichthyosis vulgaris (IV) and major predisposing factors for atopic dermatitis (AD)." (PMID 23152869, 2012). "The function of filaggrin in the development of the epidermal barrier has been confirmed in murine models of atopic dermatitis." (PMID 22619686, 2012). "Atopic dermatitis is associated with loss-of-function mutations in the filaggrin (FLG) gene, accompanied by reduced levels of filaggrin breakdown products on the skin." (PMID 21036388, 2010). "Null mutations within the filaggrin gene (FLG) cause ichthyosis vulgaris and are associated with atopic eczema." (PMID 19681860, 2009). "The rs61816761 variant in the FLG gene (c.1501C>T; p.Arg501Ter) (OMIM*135940; ICD‐11 EB00.2) is a stop‐gain mutation that leads to premature termination of the filaggrin protein, commonly associated with atopic dermatitis and ichthyosis vulgaris." (PMID 40763936, 2026). "While these findings remain preliminary and do not establish a direct genetic association between atopic dermatitis and AD, they nominate FLG as a potential biological bridge between skin-barrier dysfunction and neurodegeneration." (PMID 41465136, 2025). "Studies using filaggrin-mutant mice demonstrate that IL-1β production is significantly elevated in inflamed skin and that blocking IL-1β signaling reduces inflammation, suggesting its critical importance in the pathogenesis of atopic dermatitis." (PMID 41304926, 2025). "Exon 3 loss-of-function variants in the filaggrin gene (FLG) are frequently linked to skin barrier malfunction, with FLG LoF variants prevalent in around 25% to 30% of individuals of European and Asian descent who have atopic dermatitis." (PMID 38938453, 2024). "The disorder of FLG gene expression was observed and recorded in several dermal diseases, particularly in those related to abnormalities of keratinization and the skin barrier, such as psoriasis, ichthyosis vulgaris, atopic dermatitis, etc." (PMID 38616504, 2024). "Filaggrin plays an important role in protecting the skin barrier, retaining skin moisture, reducing inflammatory responses, and maintaining skin health, and it has a positive effect on the treatment of atopic dermatitis." (PMID 38790293, 2024). "Furthermore, the histological analysis revealed enhanced filaggrin production and a decreased number of mast cells (p < 0.05), indicating that (S)-(-)-blebbistatin O-benzoate improved atopic dermatitis symptoms in a pathological model." (PMID 38713650, 2024). "Filaggrin is important for the skin barrier and atopic dermatitis." (PMID 38338121, 2024). "The loss-of-function variant in CARD14 in atopic dermatitis leads to a decrease in NF-κB activation, epidermal secretion of antimicrobial peptides and mRNA expression of FLG, encoding filaggrin, which is an epidermal protein essential for skin barrier function." (PMID 37325658, 2023). "Interestingly, calcitriol application upregulated filaggrin, loricrin, claudin-1, and Tjp1 in NC/Nga mice with atopic dermatitis." (PMID 37298299, 2023).